MT-ND4 (mitochondrially encoded NADH:ubiquinone oxidoreductase core subunit 4)
Description:
Regulates mitochondrial respiration by decreasing oxygen consumption. Also regulates reactive oxygen species homeostasis. Core subunit of the mitochondrial membrane respiratory chain NADH dehydrogenase (Complex I) which catalyzes electron transfer from NADH through the respiratory chain, using ubiquinone as an electron acceptor. Essential for the catalytic activity and assembly of complex I.
Synonyms: ND4; NAD4; formerly MTND4; LHON
Tractability: Small molecule: an approved drug acts on it; a structure with a bound ligand is known; it belongs to a druggable protein family. Antibody: UniProt predicts a signal peptide or a membrane-spanning region. PROTAC: a small molecule that binds it is known.
Target class: Enzyme; Oxidoreductase
Chemical probes: ROTENONE
Gene: Protein-coding gene on chromosome MT (10,760 to 12,137, forward strand). Ensembl gene ENSG00000198886.
Subcellular location: Secreted; Cytoplasm; Mitochondrion; Mitochondrion inner membrane
Subcellular location (Human Protein Atlas): Mitochondria
Pathways (Reactome):
Metabolism: Complex I biogenesis; Respiratory electron transport
Metabolism of proteins: Mitochondrial translation termination
Gene Ontology:
Molecular function: NADH dehydrogenase (ubiquinone) activity; NADH dehydrogenase activity; ubiquinone binding
Biological process: mitochondrial electron transport, NADH to ubiquinone; mitochondrial respiratory chain complex I assembly; aerobic respiration; electron transport coupled proton transport; proton motive force-driven mitochondrial ATP synthesis; ATP synthesis coupled electron transport; cerebellum development; in utero embryonic development; response to ethanol; response to hypoxia; response to nicotine
Cellular component: mitochondrial inner membrane; mitochondrion; respiratory chain complex I
Gene-disease validity (ClinGen):
ClinGen rates the evidence that MT-ND4 causes each of these diseases.
Leigh syndrome (mitochondrial): Definitive. A progressive neurological disease defined by specific neuropathological features associating brainstem and basal ganglia lesions.
mitochondrial disease (mitochondrial): Definitive.
Homologues: Orthologues: chimpanzee MT-ND4 (95% identical), macaque ND4 (77% identical), pig ND4 (73% identical), rabbit MT-ND4 (72% identical), guinea pig MT-ND4 (71% identical), rat Mt-nd4 (68% identical), mouse mt-Nd4 (67% identical), tropical clawed frog ND4 (62% identical), zebrafish mt-nd4 (60% identical), Drosophila melanogaster mt:ND4 (41% identical), Caenorhabditis elegans WBGene00010963 (27% identical). Paralogues in human: MT-ND5 (19% identical), MT-ND2 (14% identical).
Diseases named in the same sentence as MT-ND4 in open-access papers:
MT-ND4 is named in the same sentence as 138 diseases in open-access papers, as found by Europe PMC text mining. Sharing a sentence is not in itself a finding about the gene and the disease. The quoted sentences say what the papers report.
Leber hereditary optic neuropathy (70 papers, 2009 to 2026). Leber's hereditary optic neuropathy (LHON) is a mitochondrial neurodegenerative disease affecting the optic nerve and often characterized by sudden vision loss in young adult carriers. "This mutation is one of the three commonmutation sites in Leber’s hereditary optic neuropathy (LHON) disease (the othertwo common pathogenic mutations are m.11778G>A in the MT-ND4 gene andm.3460G>A in the MT-ND1 gene)." (PMID 41504202, 2025). "In another patient with optic atrophy, the homoplasmic m.11778G>A variant (depth, 31) in MT-ND4 was identified." (PMID 38819824, 2024). "In particular, the mitochondrial DNA (mtDNA) primary mutation, m.11778G>A/MT-ND4 (p.R340H), pathogenic for Leber’s hereditary optic neuropathy (LHON), induced a reduction in rotenone sensitivity to its inhibitory effect in vitro." (PMID 35209128, 2022). "The here identified DNA variation in MT-ND4 has been previously shown to be associated with numerous classical mitochondrial disorders like Leber’s Hereditary Optic Neuropathy or Leigh syndrome." (PMID 27716073, 2016). "A rare MT-ND4 variant characterizing the T2 haplogroup existed in a small case study of people with Leber hereditary optic neuropathy (LHON), a blinding disease." (PMID 19434233, 2009). "The number of discovered mutations has increased at a fast pace since the identification of the first causal mutations in 1988, a point mutation in MT-ND4 and large mtDNA deletions for Leber hereditary optic neuropathy (LHON) and mitochondrial myopathy, respectively." (PMID 34114603, 2021). "The NyuWa pathogenic variant, m.11778G>A in MT-ND4, is linked to Leber hereditary optic neuropathy (LHON), a maternally inherited mitochondrial disease causing vision loss." (PMID 41206126, 2025). "In Thailand, the MT-ND4 m.11778 G>A mutation was associated with Leber hereditary optic neuropathy (LHON) but mtDNA variation in cardiovascular disease patients has not been previously reported in Thailand." (PMID 38990956, 2024). "In the third generation, an affected male (the father in this family), diagnosed with optic atrophy due to OPA1 c.2383C > T variant, married a woman (the mother) carrying the LHON MT-ND4 m.11778G > A variant." (PMID 40417638, 2025). "Various studies have shown a significant association of polymorphisms in MTND4 with age-related muscular degeneration (AMD), Leber’s hereditary optic neuropathy (LHON), mesial temporal lobe epilepsy (MTLE), and cystic fibrosis." (PMID 33895935, 2021). "For example, mutations in MT-ND1 and MT-ND4 can cause Leber hereditary optic neuropathy (LHON), a disease characterized by bilateral, painless central vision loss in early to late adulthood resulting from the specific degeneration of retinal ganglion cells in the optic nerve." (PMID 26839416, 2016). "These include the severe mutation in the tRNALys gene, m.8363G>A, and the three milder yet prevalent Leber's hereditary optic neuropathy (LHON) mutations in the MT-ND1 (m.3460G>A), MT-ND4 (m.11778G>A) and MT-ND6 (m.14484T>C) mitochondrial genes." (PMID 25909222, 2015). "Next, we tried to install two mutations at GC context in MT-ND4 and MT-ND6 that have been linked to human diseases including Leber hereditary optic neuropathy (LHON) and Leigh syndrome, which are both devastating genetic diseases with no effective therapy." (PMID 36797253, 2023). "Leber’s hereditary optic neuropathy (LHON) is a maternally inherited blinding disorder, which in over 90% of cases is due to one of three primary mitochondrial DNA (mtDNA) point mutations (m.11778G>A, m.3460G>A and m.14484T>C, respectively in MT-ND4, MT-ND1 and MT-ND6 genes)." (PMID 22879922, 2012). "Leber hereditary optic neuropathy (LHON) is the typical single organ involvement mitochondrial disorder caused by mtDNA point mutations such as genevariation on m.3460G → A MT-ND1, m.11778G → A MT-ND4, and m.14484 T → C MT-ND6." (PMID 40536597, 2025).
Leber hereditary optic neuropathy (continued). "Leber hereditary optic neuropathy (LHON) is an inherited optic neuropathy that develops predominantly as a consequence of three mtDNA point pathogenic variants, namely m.3460G > A (MT-ND1), m.11778G > A (MT-ND4), and m.14484T > C (MT-ND6)." (PMID 36294366, 2022). "The three primary mutations (m.3460G>A in the MT-ND1 gene, m.11778G>A in the MT-ND4 gene, and m.14484T>C in the MT-ND6 gene) on mitochondrial DNA (mtDNA) have been identified to be the essential factors for Leber hereditary optic neuropathy (LHON, OMIM 535000)." (PMID 22110754, 2011).
Optic neuropathy (12 papers, 2007 to 2025). "Most of them have LHON syndrome with isolated optic neuropathy due to the prevalent mutations m.11777G > A in MT-ND4, m.3460G > A in MT-ND1, or m.14484 T > C in MT-ND6." (PMID 31996177, 2020). "Genetic variations in the MT-ND4 are implicated in other optic neuropathies." (PMID 34976016, 2021).
breast carcinoma (9 papers, 2011 to 2024). "Analysis of bulk RNA-Seq revealed a decrease in WSCD2 gene expression in the samples from TCGA breast cancer patients with the genotype homozygous for the minor alleles and core gene networks of transcription factors, growth factors and insulin indirectly associated with MT-ND4." (PMID 35082309, 2022). "Five mitochondrial genes (MT-ND4, MT-ND1, MT-ND3, MT-ND6, and MT-ND2), which were identified as key genes of the complex I biogenesis pathway by Pathformer, were also reported to be associated with breast cancer prognosis." (PMID 38741230, 2024). "Comparisons of gene expression data from the TCGA breast cancer patients with the genotype homozygous for the minor alleles of the SNPs in WSCD2 and MT-ND4 versus the other genotypes revealed core transcriptional regulator interactions and an association with insulin." (PMID 35082309, 2022). "Moreover, dysfunction of MT-ND4 has been described in the context of experimental autoimmune encephalomyelitis, which is an animal model of multiple sclerosis, breast cancer, cystic fibrosis and other diseases." (PMID 27716073, 2016).
male infertility (6 papers, 2021 to 2026). The inability of the male to effect fertilization of an ovum after a specified period of unprotected intercourse. "Mutations in Prm2 and mt-Nd4 have been associated with human male infertility, suggesting their potential as diagnostic markers." (PMID 41602862, 2026). "The biological relevance of these marker genes is underscored by the fact that mutations in Prm2 and mt-Nd4 are known to be associated with human male infertility, highlighting their potential diagnostic value." (PMID 41602862, 2026). "The current study aimed to investigate the role of single-nucleotide polymorphisms (SNPs) in the MTND3, MTND4L, and MTND4 genes related to both primary and secondary male infertility by comparing their genotypic profiles using Sanger sequencing." (PMID 40843731, 2025). "An SNP called rs2853495 in the MTND4 gene was found to have an association with male infertility in the genotype frequency test." (PMID 35885965, 2022). "The purpose of the current study was to investigate whether polymorphisms in the MTND4 gene are correlated with male infertility." (PMID 33895935, 2021). "Our study is the first to explore the association between MTND4 SNPs and male infertility." (PMID 33895935, 2021). "In conclusion, we identified an as yet unknown association between mitochondrial gene polymorphisms in MTND4 and male infertility." (PMID 33895935, 2021). "Although the sample size was small, our findings suggest that the rs2853495 and rs869096886 SNPs in MTND4 might be associated with male infertility." (PMID 33895935, 2021). "Accordingly, we aimed to examine whether MTND4 polymorphisms contribute to male infertility." (PMID 33895935, 2021). "This study explored the role of single-nucleotide polymorphisms (SNPs) in mitochondrial genes (MT-ND3, MT-ND4L, and MT-ND4) in primary and secondary male infertility." (PMID 40843731, 2025). "This study analyzed the frequency of single-nucleotide polymorphisms (SNPs) in mitochondrial genes (MT-ND4, MT-ND4L, and MT-ND3) and their potential correlation with primary and secondary male infertility." (PMID 40843731, 2025). "In conclusion, our findings suggested that male infertility was correlated with rs2853495 and rs869096886 SNPs in MTND4." (PMID 33895935, 2021). "However, the overall association between MTND4 polymorphisms and male infertility remains unknown." (PMID 33895935, 2021). "Moreover, G11719A (rs2853495) and A11251G (rs869096886) in gene MTND4 were also tied to male infertility." (PMID 35885965, 2022). "However, analysis of a larger sample is needed and will allow a better understanding and clarification of the role of these MTND4 SNPs in male infertility." (PMID 33895935, 2021).
diabetes (4 papers, 2014 to 2025). "According to recent publications, during the pathogenesis of diabetes, MT-ND4 has a quite low-expression pattern and on the contrary, MT-ND5 has a relevantly higher expression level, corresponding with the prediction expression level of their agonists individually." (PMID 35721855, 2022).
glaucoma (4 papers, 2020 to 2023). Increased pressure in the eyeball due to obstruction of the outflow of aqueous humor. "However, additional research is needed to establish the regulatory function of mutation in MT-ND4, which could lead to an increase in oxidative stress and favor the development of glaucoma." (PMID 36004037, 2022). "Moreover, there are other case reports where probands with disease-causing variants in MT-ND4 develop glaucoma, suggesting that high intraocular pressure could have some effect on the oxidative stress caused by the mtDNA mutation participating in the retinal damage." (PMID 36827238, 2023).
Obesity (4 papers, 2021 to 2024). Accumulation of substantial excess body fat. "Thus, variants in its encoding genes, especially MT-ND4:11947A>G found exclusively in obese individuals, might sway cell energy metabolism, impacting body fat mass, BMI, and obesity risk." (PMID 39464187, 2024).
Infertility (3 papers, 2015 to 2025). "We first identified SNPs in the MTND4 gene by Sanger sequencing and then determined their association with infertility using a case-control study design." (PMID 33895935, 2021). "To determine whether the variations of MTND4 were related to infertility, we compared each of the genotypes and allele frequencies between the case and control groups." (PMID 33895935, 2021). "The purpose of the present study was to determine the relationship between infertility and the polymorphisms of mitochondrial NADH dehydrogenase subunit 4 (MTND4) by spermatozoa analysis in fertile and subfertile men." (PMID 33895935, 2021).
melanoma (3 papers, 2017 to 2025). A malignant, usually aggressive tumor composed of atypical, neoplastic melanocytes. "We found that in the human melanoma 1205Lu cell line, as well as in primary tumors, the expression levels of the mitochondrial genes MT-ND1 and MT-ND4 were downregulated." (PMID 36672229, 2023).
multiple sclerosis (3 papers, 2016 to 2025). A progressive autoimmune disorder affecting the central nervous system resulting in demyelination. "Mutations in MT-ND5 12633C > A and MT-ND4 11719G > A genes were found in patients with multiple sclerosis." (PMID 39802950, 2024).
prostate carcinoma (3 papers, 2020 to 2025). A carcinoma that arises from epithelial cells of the prostate gland. "Recent studies have demonstrated that detrimental alterations in mitochondrial complex I and IV genes, including MT-ND4 and MT-CO1, are linked to enhanced oxidative phosphorylation activity and increased aggressiveness in high-grade and treatment-resistant prostate cancers." (PMID 40491606, 2025). "In most tumors, except prostate cancer, genes MT-ND1 through MT-ND4, which are crucial for the assembly of ETC Complex I, showed reduced expression." (PMID 39594421, 2024).
schizophrenia (3 papers, 2009 to 2025). A major psychotic disorder characterized by abnormalities in the perception or expression of reality. "Several studies have reported that among the identified MTND4 SNPs, rs2853495 is related to ulcerative colitis and pancreatic cancer, and rs869096886 is related to schizophrenia, whereas rs2857285 is associated with a more invasive form of ovarian cancer." (PMID 33895935, 2021).
adenocarcinoma of the prostate (2 papers, 2022 to 2024). "CD8+ T cells (MT‐ND4) were implicated in glomerular disease, tumor immunity, and tumor metastasis in ccRCC, including breast and bladder cancer, fibrosarcoma of the bladder, adenocarcinoma of the prostate, lymphoma, adult fibrosarcoma, and metastases from various other tumors." (PMID 38872260, 2024).
Anxiety (2 papers, 2023 to 2025). Intense feelings of nervousness, tension, or panic often arise in response to interpersonal stresses. "There were 5 common mtDNAs shared with anxiety and depression in MiWAS, namely m.10915T>C(MT-ND4), m.3010G>A(MT-RNR2), m.9899T>C(MT-CO3), m.15257G>A(MT-CYB) and m.4580G>A(MT-ND2)." (PMID 37344456, 2023). "In addition, 4 mtDNA variants were detected to interact with CRP for both anxiety and depression, including m.12633C>A(MT-ND5), m.9899T>C(MT-CO3), m.4561T>C(MT-ND2), m.11377G>A(MT-ND4)." (PMID 37344456, 2023).
hearing loss (2 papers, 2013 to 2024). "The m.11778G>A mutation in the MT-ND4 gene is associated primarily with LHON; whereas, m.1555A>G in the 12S rRNA gene has been reported with aminoglycoside-induced non-syndromic hearing loss." (PMID 23805034, 2013).
hepatocellular carcinoma (2 papers, 2022). A malignant tumor that arises from hepatocytes. "Additionally, 10810 (MT-ND4), 12705 (MT-ND5) and 16527 (D-loop) are also shared by the same cancer types (hepatocellular carcinoma and renal cell carcinoma)." (PMID 35183124, 2022).
Kearns-Sayre syndrome (2 papers, 2020 to 2023). Kearns-Sayre syndrome (KSS) is a mitochondrial disease characterized by progressive external ophthalmoplegia (PEO), pigmentary retinitis and an onset before the age of 20 years. "Within 1 year large-scale deletions in the mtDNA causing mitochondrial myopathy (MIM 251900) or Kearns-Sayre syndrome (KSS, MIM 530000) shortly followed by an mtDNA point mutation in MT-ND4 causing LHON (MIM 5350000), were identified." (PMID 33324649, 2020).
chordoma (1 paper, 2021). Chordomas are rare malignant tumors arising from embryonic remnants of the notochord in axial skeleton. "Another recurrent LoF mutation in MT-ND4, m.11031GA>G was seen in a chordoma case and MB case." (PMID 34337412, 2021). "Additionally, 2 different chordoma cases harbored the same stop-gain mutation in MT-ND4, m.10971G>A." (PMID 34337412, 2021). "The same chordoma patient had 3 LoF mutations, 2 in MT-ND4 and 1 in MT-CO2." (PMID 34337412, 2021).
glomerular disease (1 paper, 2024). "KEGG analysis indicated that CD8+ T cell (MT‐ND4) potentially played an important role in the development and metastasis of ccRCC, nephrotic syndrome, glomerular disease, renal ischemia, ureteral stenosis, and renal metastases in ccRCC patients." (PMID 38872260, 2024).
kidney angiomyolipoma (1 paper, 2022). An angiomyolipoma arising from the kidney. "We identified three variants of uncertain significance (VUS) predicted to be pathogenic by in silico algorithms, one in MT-ND4 and two in MT-CYB occurring in a kidney angiomyolipoma, a TSC-RCC, and a LAM-associated abdominal tumor." (PMID 36793390, 2022).
meningioma (1 paper, 2021). A generally slow growing tumor attached to the dura mater. "Conversely, another patient (ID PT_HT4HJXY6) with an initial diagnosis of MB and no mtDNA mutation was later diagnosed with meningioma which had an m.11682G>A MT-ND4 missense mutation." (PMID 34337412, 2021).
mood disorder (1 paper, 2021). A cognitive disorder a disturbance in which the person's mood is hypothesized to be the main underlying feature. "We quantified mRNA levels corresponding to interneuron marker genes (PV and SST), plasticity genes known to be altered by OTX2 levels (Gadd45b, Arc, Nr4a1), and inflammatory/oxidative stress pathway genes (Mtnd4 and Iba1), given that mood disorders can be related to oxidative stress response." (PMID 33963285, 2021).
rectal cancer (1 paper, 2023). A primary or metastatic malignant neoplasm that affects the rectum. "Based on mutations per kilobase, MT-ND5 and MT-ND4 were also the most affected in WB and FFPE tissue samples, respectively, from the rectal cancer patients." (PMID 37438741, 2023).
schwannoma (1 paper, 2021). A benign, usually encapsulated slow growing tumor composed of Schwann cells. "Seven heteroplasmic mutations were identified across schwannoma samples with 3 missense mutations identified in MT-CO3, MT-ND4, and MT-CYTB." (PMID 34337412, 2021).